TERT (telomerase reverse transcriptase)
Diseases named in the same sentence as TERT in open-access papers (continued):
Sharing a sentence is not in itself a finding about the gene and the disease.
glioblastoma (continued). "Two recurrent mutations of TERTp that reach 70–80% frequency in glioblastoma are located − 124 bp and − 146 bp upstream of the TERT translation start site (chromosome 5p15.33: 1,295,228 C > T and 1,295,250 C > T, respectively C228T and C250T)." (PMID 33148330, 2020). "The TERT promoter mutation was the highest (44.9%) in the WHO IV glioblastoma, followed by WHO II oligodendroglioma with IDH mutation and 1p/19q codeletion." (PMID 32047544, 2020). "Somatic mutations within the TERT promoter (TERTp) region are involved in oncogenesis in various type of tumor including glioblastoma." (PMID 33148330, 2020). "TERT promoter mutation was predominantly found in the three main glioblastoma groups (MES, RTK I, and RTK II)." (PMID 32991787, 2020). "Mutation in TERT promoter were shown to play major role in the activation of telomerase in several tumors, such as melanoma, glioblastoma, head and neck cancer and other solid tumors." (PMID 33003326, 2020). "TERT promoter mutation, the most common genetic alteration in glioblastoma, was found at position c.-146C > T." (PMID 32014051, 2020). "Copy‐number analysis revealed association of TERT mutation with amplification of chromosome 7 and loss of chromosome 10, for example, with a typical glioblastoma phenotype in differential and WGCNA analysis." (PMID 32991787, 2020). "TERT promoter mutations occur mainly in cancers arising from tissues with low-rates of self-renewal that include glioblastoma, melanoma, urothelial carcinoma, squamous cell carcinoma, medulloblastomas, and aggressive thyroid carcinoma subtypes." (PMID 32121056, 2020). "Of note, a high frequency of TERT promoter mutations occurs in BC, melanoma, and TC, as seen in glioblastoma." (PMID 31802036, 2020). "TERT promoter mutations occur in the majority of glioblastoma, bladder cancer (BC), and other malignancies while the ETS family transcription factors GABPA and its partner GABPB1 activate the mutant TERT promoter and telomerase in these tumors." (PMID 31802036, 2020). "The TERT mutation correlates with the 1p/19qcodeletion and primary glioblastomas; it is rarely detected in grade II and IIIastrocytomas and secondary glioblastomas." (PMID 31413876, 2019). "The majority of glioblastomas can also be divided into molecular subgroups based on mutations in the telomerase reverse transcriptase (TERT) promoter." (PMID 31296788, 2019). "Recurrent, mutually exclusive point mutations in the TERT promoter were originally discovered in melanoma, and subsequently identified in other tumors, including at a high frequency in primary glioblastoma and oligodendroglioma." (PMID 30967140, 2019). "Glioblastoma, malignant melanoma, urothelial bladder cancer, myxoid liposarcoma, and certain subtypes of skin cancer and medulloblastoma exhibit the highest TERT promoter mutation rate (up to 80–90%)." (PMID 31285550, 2019). "The presence of TERT promoter mutations has recently been shown as a unfavorable prognostic factor in a number of cancer types including papillary thyroid carcinoma, glioblastoma, bladder cancer, and others." (PMID 31285550, 2019). "The highest significance for individual cancer types is seen for glioblastomas (p = 0.057) and thyroid cancer (p = 0.063), which are also the cancer types where TERT promoter mutations have previously been shown to correlate with cancer progression." (PMID 29354286, 2018). "In fact, TERT promoter mutations have been detected in 58% of primary glioblastomas and in 28% of secondary glioblastomas." (PMID 30279357, 2018). "The molecular alterations in IDH-wildtype glioblastomas include mutations in the TERT promoter, chromosome 10q loss, 7p gain or EGFR amplification, (some with an additional EGFR vIII mutation), ID2, MYCN and PDGFRA amplifications and CDKN2A/B deletions." (PMID 29098416, 2018). "The majority of glioblastomas can be classified into molecular subgroups based on mutations in the TERT promoter (TERTp) and isocitrate dehydrogenase 1 or 2 (IDH)." (PMID 29802247, 2018).
glioblastoma (continued). "The history of TERT mutations in glioblastomas is particularly interesting because these mutations represent a mechanism for increasing telomerase expression in some cancer cell types." (PMID 30279357, 2018). "Glioblastomas utilize distinct genetic mechanisms of telomere maintenance, either through TERT promoter mutation leading to telomerase activation or ATRX-mutation leading to ALT." (PMID 30279357, 2018). "TERT promoter (TERTp) mutations are found in the majority of World Health Organization (WHO) grade IV adult IDH wild-type glioblastoma (IDH-wt GBM)." (PMID 30333046, 2018). "TERT –245T>C polymorphisms has been investigated as a poor prognostic marker in several tumors, including hepatocellular carcinoma and glioblastoma." (PMID 29464027, 2018). "It has been found that TERT mutation is a promising predictor of prognosis in patients with glioblastoma." (PMID 28660218, 2017). "Glioblastomas have a high frequency of mutations in the TERT promoter and CDKN2A locus that are expected to render them resistant to both replicative and oncogene-induced senescence." (PMID 28526854, 2017). "We compared triple-positive samples with oligodendroglioma, IDH1 mutation only subgroup with astrocytoma and TERT mutation only tumors with glioblastoma since these genetic events highly represent histological diagnosis." (PMID 28915860, 2017). "Previous studies showed an association of the T349C genotype with reduced TERT expression in non-small cell lung cancer, bladder cancer and glioblastoma." (PMID 29100407, 2017). "Hotspot mutations in TERT promoter region were identified in up to 80% of adult/elderly glioblastomas but rare in pediatric glioblastomas." (PMID 26452024, 2016). "We confirmed TERT promoter mutations in glioblastomas (n = 2), which is lower than expected but demonstrates that we can detect the mutation." (PMID 27792139, 2016). "In CNS tumors, mainly in glioblastomas, where TERT promoter and ATRX mutations are mutually exclusive, it appears that both genetic mechanisms can confer similar advantages." (PMID 27657132, 2016). "Primary glioblastomas had the highest frequency of TERT promoter mutations (132/165; 80%) followed by oligodendrogliomas (19/27; 70%); astrocytomas showed the lowest frequency, with 22 out of 56 (39%) samples showing mutations." (PMID 25797251, 2015). "Accordingly, TERT promoter mutations did associate strongly with poor survival in the overall analysis of high grade tumors that included primary glioblastomas, high grade astrocytoma and oligodendrogliomas." (PMID 25797251, 2015). "In the past two years, the same two somatic TERT promoter mutations, together with additional TERT promoter mutations, have been identified in numerous other cancers, with particularly high prevalence in glioblastoma (62%) and bladder cancer (59%)." (PMID 26356674, 2015). "The overwhelming occurrence of the TERT promoter mutations and in general poor survival associated with primary glioblastoma probably precludes such an association." (PMID 25797251, 2015). "TERT promoter mutations are frequently observed in malignant melanoma, glioblastomas, hepatocellular and bladder carcinomas." (PMID 26462019, 2015). "The presence of polysomy of chromosome 7 and amplification of the epidermal growth factor receptor (EGFR) gene is associated with TERT mutations and a prognosis similar to primary glioblastoma in general." (PMID 25943885, 2015). "In the present study, 128 primary glioblastoma patients were examined for single nucleotide polymorphisms of TERT in blood and in 92 cases for TERT promoter mutations in tumors." (PMID 26143636, 2015). "In the perspectives of our further research, we will use TERT promoter mutations in addition to clinically relevant information for the separation of primary and secondary glioblastomas." (PMID 24511544, 2014). "Telomerase reverse transcriptase (TERT) is one of the top genes mutated in glioblastoma." (PMID 40564017, 2025).
glioblastoma (continued). "Furthermore, in another study, in 55% of the 358 glioblastomas analyzed, TERT promoter mutations (C228T, C250T) were detected; of the 55%, 73% had a C228T mutation, and 27% had a C250T mutation; only one glioblastoma had both mutations." (PMID 40564017, 2025). "Another study agrees with this view, suggesting that strictly defining IDH-wildtype grade II astrocytomas with TERT promoter mutation in isolation seemed insufficient to hypothesize that the tumor will manifest as glioblastoma, IDH-wildtype." (PMID 41035663, 2025). "Additional factors, such as Telomerase Reverse Transcriptase (TERT) promoter mutations, may further modulate its predictive power, emphasizing the need for a more comprehensive biomarker-driven approach to glioblastoma treatment." (PMID 41346390, 2025). "The latest 5th edition recently refined the diagnosis of glioblastoma by adopting a multi-layered integrated approach incorporating new molecular criteria such as TERT promoter mutation, EGFR amplification or chromosomal 7 + gain / chromosomal 10- loss for IDH-1 wildtype tumors." (PMID 40067514, 2025). "However, it is well-established that the TERT mutation, commonly seen in glioblastomas and oligodendrogliomas, is informative for the classification of CNS tumors." (PMID 40867242, 2025). "Notably, TERT promoter mutations were detected at much higher rates in NSCs from patients with IDH-wildtype glioblastoma than controls." (PMID 40429889, 2025). "Glioblastoma frequently exhibit TERT mutation C250T or C228T." (PMID 40244270, 2025). "Mutations in the promoter region of the TERT gene occur in 70–80% of all glioblastomas." (PMID 40564017, 2025). "These post-mortem findings in combination with identification of the TERT promoter mutation allowed for a histomolecular diagnosis of glioblastoma, IDH-wildtype, completely in line with the diagnosis suggested by nanopore sequencing of CSF during the life of the patient." (PMID 39225924, 2024). "Accordingly, this review first aims to summarize current research in recurrent glioblastoma such as the molecular pathways and genetic mutations that drive cell proliferation (TERT, PTEN, PI3K/Akt, MSH6, and LTBP4) and paracrine signaling of glioma stem cells (GSCs)." (PMID 38928445, 2024). "Sixty-three percent of the patients could be conclusively reclassified as glioblastoma based on either TERT mutation, EGFR amplification, or both." (PMID 38672254, 2024). "Although germ line variants in the TERT promoter have been described in other cancers, e.g., melanoma or glioblastoma, the described hotspot mutations represent somatic mutations and a germ line hot spot mutation that, to our knowledge, has never been described." (PMID 38392213, 2024). "The location of the glioblastoma may be used as a predictor of the status of the TERT promoter mutation." (PMID 38893240, 2024). "Additionally, the prognosis appears to worsen with the presence of TERT promoter mutations in glioblastomas with an IDH wild-type status." (PMID 38932383, 2024). "Sixty-three percent of the patients (n = 35/54) could be conclusively reclassified as glioblastoma based on either TERT mutation or EGFR amplification or both (n = 4/35)." (PMID 38672254, 2024). "However, this SNP was also coupled with reduced TERT expression and better survival in the context of activating TERT promoter mutations in other cancer types such as glioblastoma and bladder cancer." (PMID 37993930, 2023). "But the glioblastomas with TERT promoter mutation had a significantly higher ArMRS than TERT promoter wild-type glioblastomas, which suggested that the TERT promoter mutation may be associated with arginine metabolism." (PMID 37214463, 2023). "TERT promoter mutations are a hallmark of glioblastoma (GBM)." (PMID 36997627, 2023). "Importantly all cases with histopathological features of glioblastomas displayed TERT promoter mutation but also 6/14 with histopathological features of LGG cases." (PMID 36647073, 2023).
glioblastoma (continued). "Additionally, the C228T and C250T are two dominant hotspots of TERT promoter mutations found in many cancers including thyroid cancer, melanoma, urothelial cancer, and glioblastoma." (PMID 37948420, 2023). "In glioblastoma, TERT promoter mutations are considered early genetic events of tumour development." (PMID 38033865, 2023). "To elucidate whether our findings are transferable to brain tumors, we extended our analyses to glioblastoma, in which TERT promoter mutations are highly recurrent and diagnostic biomarkers." (PMID 37418389, 2023). "TERT promoter mutations are commonly found in glioblastoma and in oligodendroglioma." (PMID 35693015, 2022). "Given the high frequency of TERT mutations in glioblastoma, strategies inhibiting telomerase activity may present an attractive therapeutic target, namely inhibitors, immunotherapy, and vaccines." (PMID 35806478, 2022). "Interestingly, another group showed that glioblastoma cells carrying the alternative hotspot mutation (TERT c.-146C>T) are bound by ETS factors ETS1/2, which cooperate with non-canonical NF-kB signaling via p52 to reactivate mutant TERT." (PMID 35053525, 2022). "In IDH-wildtype glioblastomas which meet the histopathological or molecular diagnosis criteria, it remains unclear whether the presence of TERT promotor mutations provides additional prognostic information." (PMID 36325373, 2022). "TERT promoter mutation is a poor prognostic factor in IDH wild-type glioblastomas." (PMID 35806478, 2022). "Interestingly, TERT promoter mutations are frequently detected in tumors originating from normal cells with low rates of self-renewal, such as glioblastoma (83%), melanoma (71%), UBC (67%), UTUC (47%), and hepatocellular carcinoma (HCC) (44%)." (PMID 34395278, 2021). "A better understanding of the molecular mechanisms underlying TERTp-mutated glioblastoma could lead to the development of TERT-targeted therapies." (PMID 33800183, 2021). "Vice versa to IDH mutations, TERT mutations are predominantly present in glioblastoma." (PMID 33963441, 2021). "Previous studies showed that the vast majority of glioblastomas contain mutations in TERT promoter." (PMID 33763172, 2021). "Cancer-specific TERT promoter mutations, which are associated with enhanced TERT mRNA expression, are seen in ~ 19% of cancers, with higher prevalence in melanoma, bladder, glioblastoma, urothelial, thyroid and hepatocellular carcinoma." (PMID 33599797, 2021). "Approximately 70% of all adult primary glioblastomas harbor TERT promoter mutations." (PMID 34638714, 2021). "UC and glioblastoma exhibit a high frequency of TERT C228T mutation." (PMID 34395278, 2021). "Thus, TERT promoter mutations serve as a diagnostic marker to delineate histologically verified IDH-wild diffuse astrocytomas with poor outcome comparable with glioblastomas." (PMID 33228806, 2020). "TERT promoter mutations are common in oligodendrogliomas and glioblastomas." (PMID 33228806, 2020).
glioblastoma (continued). "In glioblastoma, more than 70% of the cases has the TERT promoter mutation." (PMID 30709063, 2019). "Thus, a majority of glioblastoma containing proneural subtype maintains shorter telomeres by TERT promoter mutation although there are some glioblastoma with longer telomeres by ALT activation." (PMID 30709063, 2019). "A recent study showed a very high frequency of TERT promoter mutations in primary glioblastomas." (PMID 30279357, 2018). "TERT promoter mutations alone have been linked with worse prognosis in various tumor entities such as melanoma, glioblastoma multiforme, medulloblastoma, urogenital cancer, laryngeal tumors, and with larger tumors and lymph node metastasis in the case of conventional papillary thyroid carcinomas." (PMID 29463038, 2018). "IDH1 wild type and TERT mutation tumors are commonly seen in glioblastoma." (PMID 28915860, 2017). "In contrast to germline mutations, somatic mutations in the TERT promoter occur more frequently and have been identified in several cancer types besides human melanoma, including glioblastoma, hepatocellular carcinomas, bladder cancers, thyroid cancers, and urothelial cancers." (PMID 28264499, 2017). "Recently published data indicate that within this group, tumors carrying additional TERT hotspot mutations or chromosome 10q gain, might show a poor prognosis and seem to behave clinically like glioblastomas." (PMID 27311324, 2016). "It remained to be investigated if promoter methylation of TERT causing telomerase upregulation or the alternative lengthening of telomeres (ALT) represented the major mechanism of telomere maintenance in young adult glioblastomas." (PMID 26452024, 2016). "Importantly, glioblastoma multiforme (GBM) patient tumors bearing TERT promoter mutations (C228T and C250T) known to be associated with increased telomerase activity; exhibited elevated Nrf2 and TKT expression and decreased glycogen accumulation." (PMID 27148686, 2016). "We report a significant association of certain TERT SNPs with risk of developing glioblastoma." (PMID 26143636, 2015). "Screening for TERT promoter mutations could circumvent this bias to offer individualized, more effective treatments for glioblastoma patients." (PMID 24937153, 2014). "It was also found that TERT promoter mutation frequency was significantly correlated with patient age, consistent with previous reports that age predicts poor prognosis in glioblastoma." (PMID 24937153, 2014). "Furthermore, the epigenetic upregulation of telomerase may play a role in tumor aggressiveness, and hypermethylation of TERTp can increase TERT expression, which has been implicated in glioblastoma progression." (PMID 41473634, 2025). "However, other data suggest that TERT promoter mutations may occur early in glioblastoma pathogenesis." (PMID 39796751, 2025). "Finally, it should be noted that TERT promoter mutations are frequently present in oligodendroglioma similarly to IDH-wildtype glioblastoma; this finding further highlights the importance of interpreting each molecular marker within the whole histopathological and clinical context." (PMID 37658995, 2024).